EPCAM (epithelial cell adhesion molecule)
Diseases named in the same sentence as EPCAM in open-access papers (continued):
Sharing a sentence is not in itself a finding about the gene and the disease.
colon carcinoma (continued). "Subsequently, Dalerba and Haraguchi reported that markers for colon cancer stem cells are EpCAM hi/CD44+/CD166+." (PMID 19583834, 2009). "Epithelial cell adhesion molecule was then found to be expressed at a high level and frequency not only on colon cancer tissues but on most human adenocarcinomas as well as on squamous cell carcinomas." (PMID 16404366, 2006). "Ad.C28-sCE2-transduced colon carcinoma cells expressed and secreted active CE that bound specifically to EpCAM-expressing cells." (PMID 15756257, 2005). "In this study, we investigated the utility of a replication-deficient adenoviral vector containing the cDNA encoding a secreted, EpCAM-targeted form of human liver CE2, Ad.C28-sCE2, to sensitise colon cancer tumours to CPT-11." (PMID 15756257, 2005). "The clinical efficacy of EpCAM IgG mAbs in breast and colon carcinoma is limited." (PMID 40358156, 2025). "Next, we tested EpCAM expression in human colon cancer cell lines." (PMID 40792441, 2025). "In addition, the PDA-GFET-based detection platform was used to identify EpCAM protein in real clinical samples from healthy individuals and colon cancer patients within 10 min, and the two showed significant differences (p < 0.001)." (PMID 40277521, 2025). "Multiplex IHC analysis of the tissue array of human colon cancer samples revealed that EpCAM is highly expressed in most colon cancer cases, suggesting that EpCAM-NIR-PIT could also be an effective treatment option for colon cancers." (PMID 40792441, 2025). "So, we also assessed the feasibility of EpCAM-NIR-PIT for treating colon cancers." (PMID 40792441, 2025). "Therefore, EpCAM exhibits both high specificity and sensitivity in colorectal cancer, and it is expected to provide important clues for the early diagnosis of colon cancer." (PMID 40277521, 2025). "EpCAM-specific CAR-NK-92 cells are cytotoxic to EpCAM-overexpressing colon cancer cells." (PMID 38680498, 2024). "The ability of EpCAM to induce HGFR phosphorylation suggested that this pathway might be partially responsible for tumorigenicity in colon cancer cells." (PMID 37543570, 2023). "Colon cancer PDX was the only case in which EPCAM expression was positive in the blood." (PMID 36639705, 2023). "The ability of EpCAM to regulate HGFR signaling suggests that this pathway may play an important role in regulating the progression of colon cancer." (PMID 37543570, 2023). "A recent study demonstrated that protein tyrosine kinase 7 (PTK7), a critical membrane receptor that was first discovered in colon carcinoma cell lines, improved the sensitivity of detecting CTCs in gastric cell line samples combined with epithelial cell adhesion molecule (EpCAM)." (PMID 36302755, 2022). "Most importantly, upon orthotopic injection of tumor cells preconditioned by or admixed with TASCs, significantly higher numbers of colon cancer cell were shown to metastasize into distant organs, as indicated by detection of EpCAM+ cells by flow cytometry and immunofluorescence." (PMID 35454931, 2022). "Ultimately, based on our MCIA, we identified CD15, CD104 (Integrin-β4), CD324 (E-cadherin), CD326 (EpCAM), and CD49f as biomarkers for colon cancer and CD24, CD26 (DPP4), CD106 (VCAM1), TIM-1, SSEA-3 (B3GALT5), SSEA-4 (TMCC1), TRA-1-60-R (PODXL) and EGFR for renal cancer." (PMID 36221114, 2022). "Importantly, in the present study, we found that increased levels of AhR protein can be found not only in whole colon tumor tissue, but directly in EpCAM+ epithelial cells isolated from CRC tumors." (PMID 36077780, 2022). "CD133 and EPCAM are transmembrane proteins that are typically overexpressed in colon cancer." (PMID 35267665, 2022). "Similarly, fatty acids, as well as their synthesis genes, were found to be significantly increased in EpCAM+ cells isolated from colon cancer patients." (PMID 36369033, 2022). "Further analysis indicated that p38/MAPK might be a potential target for EpCAM+/CD4+ T-cell-rich colon cancer patients." (PMID 36369033, 2022).
colon carcinoma (continued). "For example, enhanced EpCAM expression promoted invasion by preventing cell–cell adhesion and promoting immune escape, as well as activating downstream oncogenic genes in leukemia and colon cancer." (PMID 36369033, 2022). "The epithelial cell adhesion molecule (EpCAM) was first identified in colon cancer in 1979." (PMID 34111181, 2021). "Notably, the expression of EpCAM in normal tissues resulted in dose-dependent severe side effects and even death upon the infusion of EpCAM CAR T cells into BALB/c mice in a colon tumor model." (PMID 34943898, 2021). "Proteomic analysis of EVs isolated from colon carcinoma cell‐derived organoids even revealed a distinct population of exosomes according to EpCAM expression and showed a colocalization of EpCAM with CD44 and claudin 7, proteins that are known to promote tumour progression." (PMID 33343836, 2020). "Besides Sox2 and ALDH, expression of several other surface proteins, such as CD44, CD133, Lgr5, CD24, EpCAM and ABCG2, has been associated with stemness features in the context of colon cancer." (PMID 32927726, 2020). "Importantly, for the first time, we performed a detailed analysis of PL profiles in isolated primary epithelial (EpCAM-positive) colon tumor cells from CRC patients and compared them with adjacent non-tumor epithelial cells isolated from the same donor." (PMID 31999740, 2020). "Immunoblotting results showed that expression of CAM molecules, such as claudin-1, −3 and −4, EpCAM, E-cadherin, and Tspan8 were very low in normal colon cancer cell line CCD18Co compared to Caco-2, DLD-1 and SW620 colon cancer cell lines but no expression was observed in DLD-1 cells for Tspan8." (PMID 30289336, 2019). "However, when the expression analysis of B4GALT5 gene was performed in EpCAM+ cells isolated from the same colon tumor samples, its mRNA levels were increased significantly." (PMID 31801289, 2019). "In this study, we investigated the changes in the levels of cell adhesion molecules EpCAM, claudins, E-cadherin, tetraspanins, and PKCs at both protein and mRNA level after treating the colon cancer lines with PKC inhibitors (Bisindolylmaleimide I, Gö6976, and Rottlerin)." (PMID 30289336, 2019). "One of these anti-EpCAM mAbs, EpAb2-6, was found to induce cancer cell apoptosis in vitro, inhibit tumor growth, and prolong the overall survival of both a pancreatic cancer metastatic mouse model and mice with human colon carcinoma xenografts." (PMID 26317650, 2015). "In a small cohort, cleavage of EpCAM and nuclear translocation of EpICD, which was associated with the induction of proliferation, were seen primarily in colon carcinomas and not in normal mucosa." (PMID 25477371, 2015). "Therefore, this study’s results suggest that multiple mAbP CO17-1A × BR55 have a significant effect on apoptosis-mediated anticancer by suppression of ERK1/2 phosphorylation in colon cancer compared to anti-EpCAM mAb and mAbP CO17-1A." (PMID 25405740, 2014). "Thus, a positive association between EpCAM and claudin-7 was observed in our study, which is consistent with the direct interaction between EpCAM and claudin-7 demonstrated in the previous studies in colon cancer." (PMID 24727741, 2014). "In addition to CD133, CD166, CD44 and EpCAM, a potential colon cancer stem cell marker is proposed to be the somatic intestinal stem/progenitor cell marker Lgr5." (PMID 21318087, 2011). "Therefore, this adenoviral construct holds promise in GDEPT approaches for the treatment of patients with EpCAM-expressing colon cancer." (PMID 15756257, 2005). "In conclusion, high mRNA expressions for LGR5, BMI1, TET1 and TET2 in the CD133 and EpCAM positive CSCs may be a useful criterion for better identification of the cells involved in colon cancer in order to specify therapeutic targets against this type of cancer." (PMID 31057717, 2019).
colon carcinoma (continued). "Similarly, others showed that elevated expression of EpCAM and altered expression of claudins, especially increases in the expression of claudin-1, −3, −4 and downregulation of claudin-7, are closely related to the metastasis process in colon cancer cells." (PMID 30289336, 2019). "The adhesion molecules EpCAM, α2β1 and CD44 s were seen to mediate tumour cell adhesion to the peritoneum and might be particularly useful in the prevention of minimal residual disease in high-risk patients, such as patients with T4 colon tumours." (PMID 27074785, 2016). "In addition, the low levels of EpCAM in MC38 cells and non-selective distribution of transferring MC38-EVs in vivo suggest that EpCAM may be involved in detachment from the colon epithelium and subsequent remote metastasis of colon cancer cells." (PMID 27721471, 2016). "HCT8 colon carcinoma cells at the lowest density occurred as single cells at the time point of seeding and were characterised by a co-localisation of EpEX and EpICD at the plasma membrane after one day in culture, which was indicative of intact EpCAM molecules." (PMID 19925656, 2009). "In conclusion, we constructed a replication-deficient adenoviral vector containing a cDNA encoding a secreted, EpCAM-targeted form of human liver CE2 that was capable of converting the prodrug CPT-11 into its activated form, leading to enhanced toxicity of CPT-11 to colon cancer spheroids." (PMID 15756257, 2005). "EpCAM is also a CSC marker in various cancers, including colon cancer, lung, breast, pancreatic, hepatocellular carcinoma (HCC), head and neck squamous cell carcinoma (HNSCC), and oral cancers." (PMID 39996844, 2025). "We first evaluated the target cell-killing efficacy of EpCAM-targeted NIR-PIT (EpCAM-NIR-PIT) using the antibody Edrecolomab in human breast and colon cancer models characterized by high EpCAM expression." (PMID 40792441, 2025). "For example, EpCAM/CD3 BiTEs eliminated CSCs in colon cancer cell lines and primary CSCs isolated from colon cancer patient samples and blocked CRC xenograft tumor growth." (PMID 40076613, 2025). "EpCAM-binding DARPins Ac2, Ec4.1, and non-binding control DARPin Off7 were conjugated to IRDye 800CW and their binding efficacy was evaluated on EpCAM-positive HT-29 and EpCAM-negative COLO-320 human colon cancer cell lines." (PMID 37642704, 2024). "It is not unique that after chemotherapy, the expression of stem-related molecules such as EpCAM, CD326, CD24, and NANOG increased in hematological tumors, liver cancer cells, pancreatic cancer cells, colon cancer cells, and peritoneal metastasis cells." (PMID 38540708, 2024). "Epithelial cell adhesion molecule (EPCAM), which was firstly reported as a dominant antigen in human colon carcinoma as early as four decades ago, is a surface glycoprotein." (PMID 36674577, 2023). "Of the 31 patients with early-onset colon cancer and advanced adenoma, 17 had germline testing, and 3 patients had PGVs (BRCA1, monoallelic EPCAM [OMIM 185535], and monoallelic MUTYH [OMIM 604933])." (PMID 37462969, 2023). "Altogether, the results confirm that 2D monolayers and 3D spheroids derived from colon cancer cell lines can be targeted by combined CEA and EpCAM recognition following a true AND-gate logic with the Dual-RevCAR system." (PMID 38169746, 2023). "Of 31 patients with early-onset colon cancer found to have advanced adenomas, 17 had germline testing data, and 3 patients had PGVs (1 each in BRCA1, EPCAM [monoallelic], and MUTYH [monoallelic] genes)." (PMID 37462969, 2023). "EpCAM and PD-L1 were also found to be upregulated in CD4+ T cells derived from colon cancer patients, which was regarded as an ineffective immune response." (PMID 36369033, 2022). "Viable CAFs were isolated from freshly resected PD-colon tumor tissues and from SQ/FR and SQ/S tumor samples by FACS using platelet-derived growth factor receptor-α (PDGFR-α) and EpCAM antibodies." (PMID 35982950, 2022).
colon carcinoma (continued). "Wu also found that XAV939 reduces the CSC markers (EpCAM, TERT) and increases chemosensitivity in colon cancer cells by inhibiting the Wnt signaling pathway." (PMID 35717205, 2022). "In the case of human colon cancer, the tumor-forming subsets in a patient's tumor were defined using CD44, epithelial cell adhesion molecule (EpCAM also known as an epithelial-specific antigen or ESA), and CD166." (PMID 35800881, 2022). "In an analysis of a GEO dataset, expression levels of EpCAM, BCL9, and DVL1 were increased in colon cancer liver metastasis compared with primary tumors." (PMID 34790117, 2021). "(A) Flow cytometric analysis of the colon cancer cell lines HCT116 and SW480 with antibodies directed against CD44 and EpCAM." (PMID 34036938, 2021). "In another study, PEITC at the dose of 20 mg/kg suppressed the growth of EpCAM+ CSCs isolated from HCT116 cancer cells and also displayed a reduction in the tumor growth of a colon cancer xenograft mice model injected with EpCAM+ CSCs." (PMID 34358102, 2021). "Currently, colon cancer stem cell (CCSC) populations have been isolated and identified by several markers, such as CD133, CD44, CD166, Lgr5, EpCAM, ALDH1 and β-catenin." (PMID 33819194, 2021). "In particular, in colon cancer, CCSCs have been identified in established colon cancer cell lines or in primary tumors through their expression of CD133, CD44, CD166, Lgr5, EpCAM, ALDH1 and β-catenin alone or through combinations of these markers." (PMID 33819194, 2021). "High expression of EpCAM has been reported to play a key role in breast, head and neck squamous cell carcinoma, and colon cancers progression, as reported with CD133 and CD90; EpCAM is crucial for CSC proliferation, differentiation, and renewal." (PMID 32391048, 2020). "Previous studies have shown that the colon cancer stem cells isolated from HCT116 cells express high levels of PROM1 (CD133), CD44, EPCAM, SOX2, c-MYC, and NANOG." (PMID 29507661, 2018). "In our earlier studies, antibodies against CK20, EpCAM and CA19–9 were used to detect metastatic colon cancer cells and antibodies against CK18, CA9, and Cadherin 6 were used to detect renal cancer cells in lymph nodes." (PMID 30290760, 2018). "Using CD133 as a colon cancer stem cell marker has continued to be controversial as some studies have found other markers, such as CD44, EpCAM (CD326), and CD166, to be much more robust at identifying colorectal CSCs." (PMID 29984391, 2018). "LOH and immunohistochemistry supported the role of DGKI, EPCAM, and OPCML in clinical colon cancer specimens." (PMID 27047543, 2016). "The majority of colon cancer cells were positive for putative cancer stem cell markers, including CD44, CD133 and EpCAM, with the exception of KM12C cells, of which only ~55% were positive for CD133." (PMID 25789015, 2015). "In colon cancer, the CD44+/EpCAM+ or CD133+ subpopulation initiates tumorigenesis and differentiates into colon cancer cells." (PMID 26474460, 2015). "In colon cancers, certain putative cancer stem cell markers, including CD133, CD44 and EpCAM, have been used to identify colon CSCs." (PMID 25789015, 2015). "Here, we report the isolation of three distinct EV subtypes from the human colon carcinoma cell line LIM1863 – shed microvesicles (sMVs) and two exosome populations (immunoaffinity isolated A33-exosomes and EpCAM-exosomes)." (PMID 25330373, 2014). "Although EpCAM previously being considered as pan-epithelial marker in the normal human colon, its frequent expression in CSCs in breast, colon, pancreas and prostate tumors suggests that this surface epitope could be a putative marker for CSCs, particularly in human colon cancer-derived cell lines." (PMID 20691072, 2010).
colon carcinoma (continued). "Previous studies using cell suspensions of colon cancer specimens demonstrated that CD133+ cells were CK20−, whereas both CD133+ as well as CD133− cells expressed the epithelial cell adhesion molecule EpCAM." (PMID 18781171, 2008). "Examples include EpCAM aptamer–guided gold NPs, which facilitate the targeted delivery of 5-fluorouracil specifically into CRC cells, and hyaluronic acid–coated polymeric NPs designed to target CD44 receptors abundantly expressed on colon cancer cells." (PMID 40452858, 2025). "Sesquiterpenes showed hepatotoxicity in liver cancer models, while certain coumarins (e.g., murpanidin, murralongin) inhibited colon cancer metastasis by downregulating EpCAM without cytotoxicity." (PMID 41346617, 2025). "In this study, EpCAM-targeted NIR-PIT was evaluated for breast and colon cancers." (PMID 40792441, 2025). "The uptake of prepared formulations was evaluated on both EpCAMpositive human colon cancer (HT-29) and EpCAM-negative Chinese hamster ovary (CHO) cell lines." (PMID 38561432, 2024). "In cellular immunotherapy, bispecific CAR-T cells targeting EpCAM and intercellular adhesion molecule 1 (ICAM-1) have demonstrated remarkable efficacy, while EpCAM-CAR-NK92 cells exhibit a synergistic therapeutic effect with regorafenib in colon cancer." (PMID 38791091, 2024). "Moreover, antibody E3 showed stronger binding to the human colon cancer cell line HCT116, which is a well-known EpCAM-expressing line." (PMID 39595576, 2024). "To test whether endogenous EpCAM directly interacts with HGFR in HCT116 and HT29 colon cancer cell lines, we used DTSSP, a cross-linker, to stabilize the putative EpCAM-HGFR complex." (PMID 37543570, 2023). "Another explanation is that the group of determinant CTCs had not been precisely identified, exemplified by the fact that only vimentin-positive CTCs were related to patients’ outcomes rather than EpCAM-positive CTCs in colon cancers." (PMID 35646680, 2022). "In our previous study, we have successfully introduced a modified methodology for isolation of EpCAM+ (epithelial) cells from both tumor and the adjacent non-tumor tissue of colon cancer patients." (PMID 34206240, 2021). "To validate whether a correlation of EpCAM and BCL9/CTNNB1 exists in cancers, we analyzed the correlations of EpCAM and BCL9 as well as EpCAM and CTNNB1 in lung cancer, colon cancer, esophageal cancer, stomach cancer, head and neck cancer, and kidney cancer." (PMID 34790117, 2021). "Here, we analyzed in detail the phospholipid (PL), lysophospholipid (lysoPL), and fatty acid (FA) profiles of purified EpCAM+ cells, isolated from tumor and adjacent non-tumor tissues of colon cancer patients." (PMID 34206240, 2021). "They showed modification of MSNs with both EpCAM and CD44 aptamers could coordinately restrain proliferation and metastasis of SW620 colon cancer cells." (PMID 34641857, 2021). "Phosphorylation of GSK-3β at Ser9 and total β-catenin levels suggested that the suppression of EpCAM might be due to alterations in the TREM2-mediated Wnt/β-catenin signaling pathway and that TREM2 might be involved in the tumorigenicity of colon cancer." (PMID 31489935, 2019). "EpCAM is an epithelial cell-specific marker, which is highly expressed in breast, prostate, and colon cancers but not RCC." (PMID 31416266, 2019). "The mid-1990s brought about large clinical phase studies utilizing the monoclonal anti-EpCAM antibody Edrecolomab, which resulted in Food and Drug Administration (FDA) approval and market introduction of Panorex for the treatment of metastasized colon cancer." (PMID 28531111, 2017).